CPNE5 (copine 5)
Description:
Probable calcium-dependent phospholipid-binding protein that may play a role in calcium-mediated intracellular processes (By similarity). Plays a role in dendrite formation by melanocytes.
Synonyms: KIAA1599; CPN5; COPN5
Tractability: Antibody: its Gene Ontology location is reachable by antibodies, with medium confidence. PROTAC: ubiquitination databases record sites on it; its protein half-life has been measured.
Gene: Protein-coding gene on chromosome 6 (36,740,775 to 36,839,444, reverse strand). Ensembl gene ENSG00000124772.
Subcellular location: Perikaryon; Cell projection
Subcellular location (Human Protein Atlas): Cytosol
Gene Ontology:
Molecular function: protein binding; calcium-dependent phospholipid binding
Biological process: positive regulation of dendrite extension; cellular response to calcium ion
Cellular component: extracellular exosome; neuron projection; neuronal cell body; perikaryon
Genetic constraint (gnomAD): Loss-of-function variants: 37 observed, 69.99 expected, observed/expected ratio (o/e) 0.53, 90% interval 0.41 to 0.69. The upper end of that interval is the gene's LOEUF score, 0.69, which puts it in group 2 of 6, group 1 being the genes least tolerant of losing a copy. Missense variants: 585 observed, 768.84 expected, observed/expected ratio (o/e) 0.76, 90% interval 0.71 to 0.81. Synonymous variants: 305 observed, 303.76 expected, observed/expected ratio (o/e) 1, 90% interval 0.91 to 1.1.
Homologues: Orthologues: chimpanzee CPNE5 (100% identical), macaque CPNE5 (100% identical), dog CPNE5 (98% identical), pig CPNE5 (98% identical), rabbit CPNE5 (98% identical), mouse Cpne5 (98% identical), rat Cpne5 (98% identical), guinea pig CPNE5 (96% identical), zebrafish cpne5b (84% identical), zebrafish cpne5a (81% identical), tropical clawed frog cpne9 (75% identical). Paralogues in human: CPNE8 (77% identical), CPNE9 (73% identical), CPNE3 (48% identical), CPNE2 (48% identical), CPNE4 (47% identical), CPNE7 (46% identical), CPNE6 (46% identical), CPNE1 (46% identical).
Diseases named in the same sentence as CPNE5 in open-access papers:
CPNE5 is named in the same sentence as 18 diseases in open-access papers, as found by Europe PMC text mining. Sharing a sentence is not in itself a finding about the gene and the disease. The quoted sentences say what the papers report.
multiple myeloma (2 papers, 2021 to 2025). "Furthermore, multiple myeloma patients with higher CPNE5 expressions reported longer event-free survival and overall survival." (PMID 40076950, 2025). "It is also reported that multiple myeloma (MM) patients with higher CPNE5 expressions had longer event-free survival and overall survival, suggesting that CPNE5 might be used as a positive indicator for MM." (PMID 34367247, 2021). "Recent research found that high CPNE5 and CPNE9 expression might serve as positive indicators of multiple myeloma, and the expression of both genes was a better predictor of survival in multiple myeloma patients." (PMID 34367247, 2021).
Obesity (2 papers, 2024 to 2025). Accumulation of substantial excess body fat. "Further connecting both conditions, we observed up‐regulation in Cpne5 expression, previously associated with both AD and obesity, and Prokr2, a gene involved in circadian rhythms." (PMID 40944384, 2025). "Notably, Cpne5 and Olr1082 have been previously associated with both obesity‐related metabolic disorders and cognitive impairment, consistent with the MONW phenotype observed in these animals." (PMID 40944384, 2025). "Finally, single nucleotide polymorphisms (SNPs) in Copine 5 genes were associated with alcohol dependence and obesity, suggesting that Copine 5 may be involved in neuropsychiatric disorders in humans." (PMID 38540677, 2024).
Anxiety (1 paper, 2024). Intense feelings of nervousness, tension, or panic often arise in response to interpersonal stresses. "The mice performed normally in locomotor tasks and memory tests but showed decreased anxiety levels in the elevated platform and the elevated plus maze behavioral tests, suggesting that Copine 5 may be involved in regulating anxiety levels." (PMID 38540677, 2024).
chronic heart failure (1 paper, 2025). "Furthermore, the expression of CPNE5 was also significantly increased in chronic heart failure induced by TAC and acute heart failure induced by I/R." (PMID 40894904, 2025).
epilepsy (1 paper, 2025). A brain disorder characterized by episodes of abnormally increased neuronal discharge resulting in transient episodes of sensory or motor neurological dysfunction, or psychic dysfunction. "Another protein indirectly linked to epilepsy is Copine 5, a calcium-dependent phospholipid binding protein." (PMID 40076950, 2025). "However, nothing has been described about CPNE5 concerning epilepsy, although lower CPNE5 levels are significantly associated with decreased survival rates." (PMID 40076950, 2025).
esophageal squamous cell carcinoma (1 paper, 2021). Esophageal squamous cell carcinoma (ESCC) is a type of esophageal carcinoma (EC) that can affect any part of the esophagus, but is usually located in the upper or middle third. "Umeda S showed that CPNE5 expression is decreased in esophageal squamous cell carcinoma (ESCC), suggesting shorter overall survival in patients." (PMID 34367247, 2021).
heart failure (1 paper, 2025). Inability of the heart to pump blood at an adequate rate to meet tissue metabolic requirements. "The in vivo experiments also showed that the cardiomyocytes-specific overexpression of CPNE5 can improve cardiac dysfunction in a mouse heart failure model and inhibit cardiomyocyte apoptosis by reducing the expression of FAS protein." (PMID 40894904, 2025). "Although in this study we have elucidated part of the mechanism by which CPNE5 exerts a protective role in the heart during heart failure, we lack clinical experimental evidence." (PMID 40894904, 2025). "The next step could involve collecting human heart failure samples to clarify the changes in CPNE5 and validating its protective effects in human pluripotent stem cell-derived cardiomyocytes." (PMID 40894904, 2025).
Myocardial fibrosis (1 paper, 2025). "In accordance with myocardial fibrosis, we detected substantially increased apoptosis in control mice (AAV9-Ctrl) but not in CPNE5 overexpressing mice (AAV9-OE-Cpne5) after TAC." (PMID 40894904, 2025).
cancer (1 paper, 2022). A tumor composed of atypical neoplastic, often pleomorphic cells that invade other tissues. "Some genes consistently indicated a positive prognosis in different cancer types, such as CD20, ADAM28, MEF2C, CPNE5, and ATP2A3." (PMID 35634306, 2022).
tumour (1 paper, 2023). "The eight probes extracted from the RFECV method showing discriminative power between tumour and nontumour samples included cg17105014 (GYPC), cg23273897 (MME), cg22083047 (PRICKLE2), cg09396217 (ANGPT1), cg01049530 (BMP3), cg18237405 (CPNE5), cg12741420 (IRF4) and cg11754206 (KCNB2)." (PMID 36779430, 2023).
CPNE5 also shares sentences with these, for which no sentence is quoted: alcohol dependence (1 paper); cognitive decline (1); Cognitive impairment (1); COVID-19 (1); infection (1); ischemia (1); metabolic disorders (1); periodontitis (1).